RAC1 (Rac family small GTPase 1)
Diseases named in the same sentence as RAC1 in open-access papers (continued):
Sharing a sentence is not in itself a finding about the gene and the disease.
prostate carcinoma (continued). "Research has been suggested that the combination of VEGF/VEGFR-targeted therapy with RAC1 inhibitor can improve the efficacy of anti-metastasis therapy in prostate cancer." (PMID 37202394, 2023). "PI3K/Akt activation by Rac1, a G-protein from the Rho family, can promote prostate cancer cell migration." (PMID 36438913, 2022). "On the other hand, some studies have suggested that mTOR complexes regulate EMT via RhoA and Rac1 signaling pathways in prostate cancer." (PMID 33920031, 2021). "miR-146a-5p presents anti-migratory effect on prostate cancer cells partially through targeting Rac1." (PMID 34517910, 2021). "Here, we demonstrate that aggressive androgen-independent prostate cancer cells display marked hyperactivation of Rac1." (PMID 32092966, 2020). "Second, we demonstrated that the Rac-GEF P-Rex1, which has been previously reported as a key Rac1 activator in prostate cancer models, is dispensable for conferring Rac1 hyperactivation." (PMID 32092966, 2020). "Considering the essential roles Rac1 and related GTPases proteins have in metastasis, deciphering the molecular mechanisms behind their unusual regulation in prostate cancer is of utmost importance." (PMID 32092966, 2020). "To further validate the P-Rex1 independence of Rac1 activation in prostate cancer cells, we examined the effect of the PI3K inhibitor BKM120 and gallein, an agent that disrupts Gβγ signaling." (PMID 32092966, 2020). "In contrast, androgen-dependent LNCaP prostate cancer cells, which have a low basal Rac1-GTP level, displayed a moderate increase in Rac1-GTP in response to serum, peaking at 15 min." (PMID 32092966, 2020). "This raises the possibility that yet unidentified regulatory mechanisms take place in the control of Rac1 activation in prostate cancer cells." (PMID 32092966, 2020). "First, we demonstrated that aggressive androgen-independent prostate cancer cell lines have markedly increased levels of activated Rac1, an effect also observed for the related G-protein Cdc42." (PMID 32092966, 2020). "It has also been reported that the active form of RAC1-GTP in prostate cancer cells promotes both survival and androgen receptor-independent cell growth." (PMID 32545340, 2020). "Recent work has also demonstrated that the spatial regulation of Rac1 activation in prostate cancer cells, an essential component of directed cell migration, is dependent on RhoH signaling." (PMID 32092966, 2020). "Towards the goal of better understanding the relevance of Rac1 signaling in prostate cancer, here, we investigated the activation status and mechanisms of regulation of Rac1 in prostate cancer cell models." (PMID 32092966, 2020). "The small-molecule inhibitor ZCL278 that blocks CDC42–intersectin (ITSN) interactions and its more potent analogue ZCL367 that also inhibits RAC1 have shown preclinical promise in prostate cancer." (PMID 33105713, 2020). "In a further effort to elucidate the mechanisms responsible for mediating Rac1 hyperactivation in androgen-independent prostate cancer cells, we performed mass spectrometry with the goal of identifying Rac1 binding partners." (PMID 32092966, 2020). "In prostate cancer cells, miR-146a-5p negatively regulates protein Rac1, which is related to cancer cell migration, thus affecting the development of metastasis." (PMID 30611259, 2019). "As a tumour suppressor, miR-146a suppresses the anchorage-independent growth, migration and invasion of prostate cancer cells by directly targeting the Rac1 gene." (PMID 30381359, 2018). "AZA1 downregulates Rac1 and Cdc42 activity in PC-3 human prostate cancer cells and inhibits the proliferation and migration of those cells as well as decreasing formation of lamellipodia and filopodia in which Cdc42 and Rac1 play a crucial role." (PMID 29596304, 2018).
prostate carcinoma (continued). "Previous in vitro and in vivo studies in prostate cancer demonstrated a marked increase in RAC1 activity in cell migration and invasion, and that RAC1 inhibition immediately stopped these processes." (PMID 29713020, 2018). "Rac1 activity is regulated by Src in many cell types and elevated expression of Rac1 is observed in prostate cancer cells and tumors." (PMID 28257035, 2017). "Rac1 has been found to be overexpressed in testicular, breast and prostate cancer, as well as gastric and lung cancers." (PMID 27104658, 2016). "A recent publication showed that APO suppressed prostate cancer and that the reduction of Rac1 and NFκB phosphorylation was involved." (PMID 26788250, 2016). "Rac1 enhances tissue invasion of prostate cancer cells by activating Rho GTPases and promoting activation of MMPs, and Akt phosphorylates Rac1 at Ser71 to inhibit its GTPase activity." (PMID 25888628, 2015). "We previously demonstrated that ATP induced activation of Rac1 and Cdc42, promoted the formation of lamellipodia and filopodia, and increased the motility of prostate cancer cells, indicating a possible role of P2Y2 receptor in prostate cancer cell motility." (PMID 26182292, 2015). "It inhibits Rac1-mediated cell functions and was reported to reverse tumor cell invasiveness in prostate cancer cells." (PMID 24810913, 2014). "Using this system, we revealed the role of phosphatidylinositol 3-kinase (PI3K) in Rac1-dependent lamellipodial motility in PC-3 prostate cancer cells." (PMID 24848679, 2014). "To clarify the relevance of PI3K to Rac1-dependent lamellipodial motility, we applied the PA-Rac1 system to prostate cancer cells." (PMID 24848679, 2014). "It is reported that radixin can regulate cell migration and cell-cell adhesion through Rac1 activation in prostate cancer cells." (PMID 25136657, 2014). "Deregulated Rho GTPases Rac1 and Cdc42 have been discovered in various tumors, including prostate and Rac protein expression significantly increases in prostate cancer." (PMID 24040362, 2013). "The activity of Rac1 was up-regulated over threefold after stimulation of 22Rv1 prostate cancer cells with EGF when compared to untreated cells." (PMID 24040362, 2013). "We now report the identification and biological activity of AZA1, a novel dual Rac1 and Cdc42 inhibitory compound that retards prostate cancer growth effectively in a human prostate cancer xenograft model." (PMID 24040362, 2013). "Cyclin D1 expression significantly decreased following Rac1/Cdc42 inhibition in prostate cancer cells." (PMID 24040362, 2013). "A variety of activators of Rac1 have been shown to be important in prostate cancer progression or in the acquisition of an invasive phenotype." (PMID 23300597, 2012). "Further, our data indicated that dimerization of protein 14-3-3ζ is necessary for the activation of Rac1, which in turn, regulates motility and transendothelial migration of prostate cancer cells." (PMID 22808202, 2012). "By contrast, in TSU-Pr1 cells (also derived from prostate cancer cells) GnRH favors cell migration through mechanisms mediated by the GTPasas Rac1 and Cdc42, and by formation of filipodia and lamellipodia." (PMID 23176180, 2012). "In conclusion, we identify 14-3-3ζ and Rac1 as novel partners in the pathway regulating prostate cancer cell-matrix interactions, motility in response to invasive and metastatic stimuli as well as for intravasation of prostate cancer cells." (PMID 22808202, 2012). "We also find that Rac1 GTPase mediates tight binding of prostate cancer cells to bone marrow endothelial cells and promotes retraction of endothelial cells required for tumor cell diapedesis." (PMID 21776386, 2011). "Our data suggest that Rac1 is required for the activation of β1 integrins leading to binding of the prostate cancer cell to the BMEC." (PMID 21776386, 2011). "Together, our data suggest that Rac1 GTPase is key mediator of prostate cancer cell-bone marrow endothelial cell interactions." (PMID 21776386, 2011).
prostate carcinoma (continued). "Additionally, RAC1 nuclear localization is also predominantly detected in prostate cancer tissues compared to benign tissues." (PMID 40396280, 2024). "Besides, other mechanisms exist for Snail-mediated cell migration, including formation of lamellipodia upon activation Rac1 and the promotion of neurite outgrowth in prostate cancer." (PMID 37095090, 2023). "Likewise, we previously showed that WHSC1 cooperates with Pten deficiency to promote prostate cancer metastasis through the regulation of AKT and Rac1 signaling." (PMID 35230972, 2022). "It is also possible that RAC1 inhibitors may be valuable in treating other diseases, such as AR-positive prostate cancer." (PMID 34373577, 2021). "The inhibitory effects of Arf6 downregulation on the migration and invasion of prostate cancer cells may be related to the decrease of Rac1 expression." (PMID 32822124, 2020). "Finally, our results revealed an unexpected mechanism of Rac1 and Cdc42 deactivation in aggressive androgen-independent prostate cancer cells." (PMID 32092966, 2020). "In this study, we investigated the regulation of Rac1 in prostate cancer cellular models." (PMID 32092966, 2020). "Such a mechanism may be quite restricted by the localization of Rac1 and Cdc42 in androgen-independent prostate cancer cells." (PMID 32092966, 2020). "We therefore sought to define whether P-Rex1 was responsible for the high basal Rac1-GTP levels observed in prostate cancer cell lines." (PMID 32092966, 2020). "Downregulating Rac1 expression by siRNA or protein inhibitors can reduce the formation of dendritic pseudopods on the surface of cell membrane by inhibiting the skeleton remodeling of prostate cancer cells and suppress their metastasis." (PMID 32822124, 2020). "To study whether the inhibitory effects of Arf6 downregulation on the proliferation, invasion, and migration of prostate cancer cells were related to Rac1, we detected Rac1 protein expression." (PMID 32822124, 2020). "Along this line, no other Rac1-GEF or mutations in Rac1 itself or in RhoGDIs could explain the elevation of Rac1-GTP in androgen-independent prostate cancer cells." (PMID 32092966, 2020). "Moreover, downregulating Rac1 expression can significantly inhibit the proliferation, invasion and metastasis of prostate cancer cells." (PMID 32822124, 2020). "Therefore, elevated Rac1-GTP levels in androgen-independent prostate cancer cells are insensitive to Rac-GAP inactivation." (PMID 32092966, 2020). "Interestingly, on average there is a three-fold increase in the ratio of Rac3/Rac1 expression levels in all prostate carcinomas when compared with the respective normal counterparts." (PMID 31514269, 2019). "Taken together, the results suggest that CRMP4 down-regulates MMP-9 expression and inhibits Rac1 GTPase by enhancing phosphorylation of Rac1 and Akt through direct interaction with Rac1 and Akt, eventually leading to suppression of prostate cancer invasion and metastasis." (PMID 25888628, 2015). "It is known that Rac1 enhances prostate cancer invasion through activation of Rho GTPases and MMPs." (PMID 25888628, 2015). "Additionally, the inhibition of Rac1 activity blocks the migration and invasion of prostate cancer cells." (PMID 24848679, 2014). "Therefore, the inhibition of PI3K activity effectively obstructs the Rac1-overexpression-mediated migration of prostate cancer cells." (PMID 24848679, 2014). "In prostate cancer cell lines, aPKCξ is activated by Src-Rac1 signaling." (PMID 24868468, 2014). "We therefore propose that a small-molecule inhibitor therapy targeting Rac1/Cdc42 Rho GTPase signaling pathways may be used as a novel treatment for patients with advanced prostate cancer." (PMID 24040362, 2013). "A recent report showing that PAK1 signaling is critical to medulloblastoma cell migration suggests that reduced PAK1 activity mediated through Rac1 inhibition in our prostate cancer model may also account for the suppressed cell migration observed." (PMID 24040362, 2013).
prostate carcinoma (continued). "We propose that AZA1 could serve as a dual, Rac1 and Cdc42-targeting, small molecule inhibitor in the treatment of patients with advanced prostate cancer." (PMID 24040362, 2013). "Thus, the observed unchanged activity of p38 and JNK following Rac1/Cdc42-inhibition by AZA1 suggests that these pathways play no major role in mediating AZA1-induced anti-proliferative effects in 22Rv1 prostate cancer cells." (PMID 24040362, 2013). "In the current study, we determined whether over-expression and dimerization of protein 14-3-3ζ leads to Rac1-mediated activation of Pak1/2 in prostate cancer cells." (PMID 22808202, 2012). "Elevated Rac1 is required for invasive behavior of the human prostate cancer cell line PC3." (PMID 23300597, 2012). "Additionally, increased expression of certain Rac1 GEFs correlates with increased biochemical recurrence and decreased disease free survival in prostate cancer patients." (PMID 23300597, 2012). "For these reasons, we determined whether ectopic expression of miR-23b/-27b in aggressive prostate cancer cells affected Rac1 activity." (PMID 23300597, 2012). "Our results demonstrate for the first time that 14-3-3ζ enhances prostate cancer cell-matrix interactions, motility and transendothelial migration in vitro via activation of Rac1-GTPase and is an important target for therapeutic interventions for prostate cancer." (PMID 22808202, 2012). "RAC1, which has been demonstrated to be upregulated in enzalutamide-resistant prostate cancer cells, plays a crucial role in enzalutamide resistance and could be a potential target for the treatment of castration-resistant prostate cancer." (PMID 34858477, 2021). "In this study, after Arf6 was downregulated, both the cell proliferative capacity and Rac1 expression reduced, indicating that the molecular mechanism by which prostate cancer cell proliferation was suppressed by Arf6 downregulation may be the downregulation of Rac1 expression." (PMID 32822124, 2020). "However, there are limited studies on the regulation of Rac1 in prostate cancer." (PMID 32092966, 2020). "Moreover, AZA1-treatment also resulted in Rac1 and Cdc42 inhibition associated with suppression of cell proliferation in EGF-stimulated androgen-independent cell lines DU 145 and PC-3 in vitro, supporting the potential of AZA1 for use in prostate cancer." (PMID 24040362, 2013). "Since PAK1 can also regulate cell transformation and survival and because of increased frequency of phosphorylation observed in poor outcome tumors, the PAK signaling pathway could therefore constitute a major effector pathway of Rac1/Cdc42 in prostate cancer cells." (PMID 24040362, 2013). "Mechanistically, we found that introduction of miR-23b/-27b in metastatic, castration-resistant prostate cancer cell lines resulted in a significant attenuation of Rac1 activity without affecting total Rac1 levels and caused increased levels of the tumor suppressor E-cadherin." (PMID 23300597, 2012). "Finally, Rac1 regulates binding of prostate cancer cells to the bone marrow endothelial cells." (PMID 21776386, 2011). "miR-574-3p can suppress target genes, as RAC1 and EP300 both identified its role in stimulating VEGF-mediated angiogenesis, and genistein used to treat prostate cancer can upregulate miRNA-574-3p and thus be used to treat cancer." (PMID 37298699, 2023). "Both RAC1-specific and dual RAC1/CDC42 inhibitors (NSC23766 and AZA1, respectively) have shown preclinical efficacy in prostate cancer cell lines (including PTEN-null PC-3 cells), inhibiting both cell migration and in vivo tumor growth." (PMID 33105713, 2020). "In summary, our work identified Rac1 and Cdc42 hyperactivation in aggressive androgen-insensitive DU145 and PC3 prostate cancer cell lines." (PMID 32092966, 2020). "Inhibiting the small GTPases, Rap1 or Rac1, generally lowered adhesion of PC3 prostate cancer cells." (PMID 25644492, 2015).
prostate carcinoma (continued). "In contrast, incubation of prostate cancer cells with EPA and DHA reduced the protein expression of GTPases (rac1, rac2 and cdc42) (abstract only)]." (PMID 25971815, 2015). "Recently, the overexpression of a Rac1 activator protein (14-3-3 protein zeta) and several GEFs (VAV3, P-Rex1) was identified in prostate cancer." (PMID 24848679, 2014). "Although several studies have shown that PI3K inhibitors obstruct the migration of prostate cancer cells as induced by chemical mediators, those studies assumed that PI3K affected the upstream signal transduction of Rac1." (PMID 24848679, 2014). "Treatment of 22Rv1 human prostate cancer cells with 5, 10 or 20 μM AZA1 for 60 min dose-dependently reduced Rac1 activity significantly by 45% (p<0.022), 70.4% (p<0.004) and 85.7% (p<0.002), respectively, compared to 20 μM NSC23766." (PMID 24040362, 2013). "Intracellularly, podocalyxin has been found to form complexes with ezrin and to influence the activities of Rac1, MAPK, and PI3K, increasing the metastatic potential of breast, kidney and prostate cancers." (PMID 21533279, 2011). "We herein demonstrate that the cross-linking of cell surface PSMA with specific antibodies activates the small GTPases RAS and RAC1 and the MAPKs p38 and ERK1/2 in prostate carcinoma LNCaP cells." (PMID 19242540, 2009). "Based on the results of the current study, we conclude that Gαi2 plays a crucial role in lamellipodia formation and cell migration in prostate cancer cells, and these effects do not depend on the activation of the Rac1 protein." (PMID 40141305, 2025). "We conclude that activated Gαi2 plays a crucial role in cell migration in prostate cancer cells independent of Rac1 activation." (PMID 40141305, 2025). "The novel findings in this manuscript show that activated Gαi2 plays a crucial role in the induction of cell migration in prostate cancer cells and this effect of Gαi2 does not require Rac1 activation." (PMID 40141305, 2025). "In prostate cancer, NRP2, mediates bevacizumab resistance via a VEGF/NRP2/PREX1/RAC1 pathway." (PMID 35875157, 2022). "Our data presented here outline the possibility that CdGAP/ARHGAP31, a negative regulator of Rac1 and Cdc42, acts as an oncoprotein rather than a tumor suppressor in prostate cancer." (PMID 34493786, 2021). "Based on these results, we concluded that no single Rac-GEF tested is responsible for Rac1 hyperactivation in prostate cancer." (PMID 32092966, 2020). "In their study, the RAC1 gene knockdown inhibited the AKT phosphorylation by upstream inputs of (Speckle-type POZ (pox virus and zinc finger protein) protein) SPOP-mutant therapy-resistant prostate cancer cell lines." (PMID 32545340, 2020). "Silencing other PI3K-dependent Rac-GEFs expressed in prostate cancer cells, namely Tiam1, Vav2 or Vav3, also failed to reduce Rac1-GTP levels in PC3 cells." (PMID 32092966, 2020). "In order to establish whether changes in Rac1 expression or activation occur in aggressive prostate cancer cells, we first determined the total and active (GTP-bound) Rac1 levels." (PMID 32092966, 2020). "Another scenario is that the Rac1-GTP pool in androgen-independent prostate cancer cells is located in a cellular compartment that is not accessible to regulatory proteins." (PMID 32092966, 2020). "The present study demonstrates that Rac1 hyperactivation occurs in aggressive androgen-independent prostate cancer, and that this is independent of P-Rex1 Rac-GEF activity." (PMID 32092966, 2020). "Downregulating Arf6 expression can inhibit the proliferation, migration and invasion of prostate cancer cells in vitro, which may be related to ERK1/2 phosphorylation and Rac1 downregulation." (PMID 32822124, 2020). "We have also demonstrated that targeting P-Rex1, a previously identified therapeutic target candidate, is unlikely to have an impact on Rac1 activation status, migration or invasion in prostate cancer cells." (PMID 32092966, 2020).